IL18 (interleukin 18)
Diseases named in the same sentence as IL18 in open-access papers (continued):
Sharing a sentence is not in itself a finding about the gene and the disease.
hidradenitis suppurativa (3 papers, 2022 to 2025). A chronic suppurative and cicatricial disease of the apocrine glands occurring chiefly in the axillae in women and in the groin and anal regions in men. "Here, we present a rare case of longstanding hidradenitis suppurativa (HS) with phrynoderma-like changes, extensive scarring, and markedly elevated IL-18." (PMID 39834723, 2025). "Activated caspase-1 and increased expression of NLRP3 and IL-18 were seen in skin biopsies from hidradenitis suppurativa patients, suggesting the potential involvement of pyroptotic cell death in this disease." (PMID 35929827, 2022). "Inflammasome activation and IL-1β and IL-18 release are also seen in pyogenic arthritis, pyoderma gangrenosum, and acne (PAPA) syndrome and in hidradenitis suppurativa." (PMID 35929827, 2022).
Hydrocephalus (3 papers, 2021 to 2024). Hydrocephalus is an active distension of the ventricular system of the brain resulting from inadequate passage of CSF from its point of production within the cerebral ventricles to its point of absorption into the systemic circulation. "IL-18 is elevated in CSF from preterm infants with posthemorrhagic hydrocephalus and hydrocephalus associated with spina bifida and aqueductal stenosis." (PMID 34863228, 2021). "aSAH patients presented significantly higher levels of caspase-1, IL-18, and IL-1β in CSF for all timepoints when compared with hydrocephalus patient controls." (PMID 39195261, 2024). "We identified six inflammatory markers, IL-6, IL-1β, LRG, IL-18, VEGF, and IFN- γ, which were associated with the most evidence of increased levels in CSF from patients with hydrocephalus compared to control subjects." (PMID 33613789, 2021). "Despite the heterogenous control group, we demonstrate that aSAH patients had significantly higher levels of ASC, caspase-1, IL-18, and IL-1β up to 5 days post-injury when compared to hydrocephalus non-aSAH patient controls." (PMID 39195261, 2024). "IL-6, IL-1β, LRG, IL-18, VEGF, and IFN-γ are elevated in CSF from patients with hydrocephalus and may be involved in promotion of hydrocephalus development and progression." (PMID 33613789, 2021).
Hypercholesterolemia (3 papers, 2018 to 2024). An increased concentration of cholesterol in the blood. "The result revealed that the AC haplotype of 2 IL-18 SNPs was also associated with lower risk of hypercholesterolemia, lower levels of CHOL and LDL-C (p=0.01, p=0.001 and 0.003)." (PMID 38774744, 2024). "The main findings of this work were the obvious associations between genotypes AA and CC of two IL-18 SNPs (rs3882891 and rs1946518) and lower risk of hypercholesterolemia, lower circulating CHOL and LDL-C levels, which may contribute to the progression of CAD." (PMID 38774744, 2024).
hypertrophic cardiomyopathy (3 papers, 2016 to 2025). A condition in which the myocardium is hypertrophied without an obvious cause. "With respective to the results of IPA, IL-18 has been considered to play an important role in progression of hypertrophic cardiomyopathy." (PMID 27888626, 2016).
idiopathic inflammatory myopathies (3 papers, 2021 to 2025). "IL-6, IL-15, and IL-18 have been noted to be elevated systemically in patients with idiopathic inflammatory myopathies (IIM)." (PMID 41488665, 2025).
internal carotid artery stenosis (3 papers, 2015 to 2024). Carotid stenosis is a narrowing or constriction of the inner surface (lumen) of the carotid artery, usually caused by atherosclerosis. "For example, enhanced IL-18 mRNA expression may not only increase the severity of internal carotid artery stenosis but also cause a similar increase in blood pressure." (PMID 39247699, 2024). "A significant relationship was identified between interleukin-18 expression and internal carotid artery stenosis severity in patients with carotid artery stenosis (p=0.051)." (PMID 29485097, 2018). "Interleukin-18 mRNA expression may affect carotid artery stenosis etiopathogenesis and internal carotid artery stenosis severity and also may play a mechanistic role in the pathogenesis of carotid artery stenosis, influencing the appearance of symptoms." (PMID 29485097, 2018).
intracerebral hemorrhage (3 papers, 2021 to 2024). A cerebrovascular disorder characterized by bleeding into one or both cerebral hemispheres including the basal ganglia and the cerebral cortex. "IL-18, produced by activated macrophages and involved in neuroinflammation, was correlated with poor outcomes in intracerebral hemorrhage." (PMID 35720096, 2022). "For instance, in the model of intracerebral hemorrhage, Dectin-1 signaling pathway upregulates the expression of GSDMD-N, IL-1β and IL-18 in mouse brain cells." (PMID 38459541, 2024).
irritable bowel syndrome (3 papers, 2021 to 2024). Irritable bowel syndrome (IBS) is a chronic functional condition of the lower gastrointestinal (GI) tract characterized by abdominal pain or discomfort and disordered bowel habit (diarrhea, constipation, or fluctuation between the two). "Also, EA stimulation can alleviate irritable bowel syndrome by regulating IL‐18 and gut microbial dysbiosis in a trinitrobenzene sulfonic acid‐induced post‐inflammatory animal model, supporting a potential positive effect of EA in visceral hypersensitivity and gastrointestinal tract." (PMID 39119947, 2024).
legionellosis (3 papers, 2015 to 2023). Any disease caused by Legionella bacteria. "Two factors, MIP and IL-18, were identified in both Table II and the legionellosis pathway." (PMID 25585621, 2015). "In animal models of Legionella infection, it has indeed been proven that the NLR family CARD domain containing 4 (NLRC4) inflammasome drives pyroptosis through caspase-1 activation and IL-18 release." (PMID 37965258, 2023).
leptospirosis (3 papers, 2014 to 2022). A contagious bacterial infection caused by spirochetes of the genus Leptospira. "Then, a cascade of inflammation is activated in the renal tubular cells, as leptospirosis induces interleukin (IL)-1β and IL-18 secretion from human macrophage cells through reactive oxygen species and cathepsin B mediated-NLRP3 inflammasome activation." (PMID 35203344, 2022). "Several clinical trials are assessing the efficacy of IL-18 inhibition in primarily chronic inflammatory diseases, but their application to leptospirosis will require consideration of potential protective roles for IL-18." (PMID 27812211, 2016). "Together, these data suggest CHI3L1, IL-18, and HGF represent new potential prognostic and therapeutic strategies for leptospirosis." (PMID 27812211, 2016).
Lymphadenopathy (3 papers, 2015 to 2025). Enlargement (swelling) of a lymph node. "A plausible hypothesis is that lymphadenopathy reflects heightened systemic inflammation and immune activation driven by excessive cytokine production (e.g., IL-1β, IL-6, IL-18)." (PMID 39797367, 2025). "These mice in comparison to IL-18-competent MRLlpr mice show reduced signs of renal pathogenesis, while other parameters such as mean survival time, lymphadenopathy, constitutive interferon-γ production, and frequency of CD3+B220+ abnormal T cells were without differences." (PMID 26465326, 2015).
macular edema (3 papers, 2019 to 2021). "On the other hand, higher concentrations of IL-18 in the aqueous humor of patients with macular edema secondary to CRVO treated with ranibizumab have been shown." (PMID 34069173, 2021). "More recently it has been demonstrated in a clinical cohort that individuals with macular oedema due to retinal vein occlusion who have high aqueous levels of IL-18 at baseline have better visual outcomes following anti-VEGF administration than those with low levels of IL-18 at baseline." (PMID 31293586, 2019).
mastitis (3 papers, 2021 to 2024). Inflammation of breast tissue during lactation or postpartum due to an obstructed duct or infection. "The proteins crucial for acute mastitis (IL-18, Il-1β, TNFα, CCL2, CCR1) demonstrate low expression." (PMID 34663465, 2021). "Through bioinformatics investigation, IL8, IL10, IL18, and CTSC were recognized as the essential biomarkers for E. coli mastitis and were related to the immune response of bovine mastitis." (PMID 34637035, 2021).
metastatic disease (3 papers, 2013 to 2022). "Nevertheless, we found a significant upregulation of IL-18 in patients with metastatic disease." (PMID 36294509, 2022).
Mycoplasma pneumonia (3 papers, 2016 to 2025). "The serum levels of IL-8, IL-10, and IL-18 increased significantly in patients with mycoplasmal pneumonia compared with those in controls (P<0.01)." (PMID 26751073, 2016). "Moreover, ATF3 can inhibit the release of inflammatory factors TNF‐α, IL‐1β, IL‐6, and IL‐18 induced by Mycoplasma pneumonia." (PMID 37385291, 2025). "IL-8, IL-18 and IL-10 level in serum were higher in people with mycoplasmal pneumonia." (PMID 26751073, 2016). "IL-18 serums level in adult with severe mycoplasmal pneumonia was significantly higher than those in patients with mild cases, suggesting that pulmonary lesions may be modulated in M. pneumoniae infected humans." (PMID 26751073, 2016). "Patients with mycoplasmal pneumonia had significantly higher CRP, IL-8, IL-10, and IL-18 levels than control subjects." (PMID 26751073, 2016). "One in vitro study of MGD on serum of children with Mycoplasma pneumonia also showed that MGD suppressed L-1β, IL-18, TNF-α, down-regulated NLRP3, pro-IL-1β, Caspase-1, pro-Caspase-1, and GSDMD-N in infected cultures and mitigated NLRP3 overexpression-induced pyroptosis." (PMID 36120338, 2022).
myelofibrosis (3 papers, 2023 to 2025). A partial or complete replacement of the bone marrow stroma by fibrous tissue. "In myelofibrosis PBMCs, IL18 was significantly up-regulated in HSCPs, myeloid and erythroid cells, confirming that increased IL18 expression is associated with progressing fibrosis and that myeloid cells are a central source of this cytokine." (PMID 41602903, 2025). "We next investigated IL18 expression in peripheral blood mononuclear cells (PBMCs) during homeostasis (healthy controls) and myelofibrosis using published single-cell transcriptomic datasets." (PMID 41602903, 2025). "High cfDNA levels participate in myelofibrosis inflammatory state, at least in part, by triggering inflammasome activation in monocytes, which results in the release of IL-18 contributing to elevated IL-18 in circulation." (PMID 38035089, 2023). "It was characterized by interleukin (IL)-6, IL-18, IL-18 binding protein (BPa), and CXCL9 chemokine hypercytokinemia accompanied by myelofibrosis." (PMID 37347054, 2023).
myeloid leukemia (3 papers, 2009 to 2022). A clonal proliferation of myeloid cells and their precursors in the bone marrow, peripheral blood, and spleen. "Research has shown that IL-18 promoted the invasive ability of HL-60 human myeloid leukaemia cells by up-regulating MMP9 expression." (PMID 36353102, 2022). "IL-12, IL-15, and IL-18 enable NK cells to further mature, and induce memory-like functions to strengthen their cytotoxicity toward myeloid leukemia." (PMID 28915651, 2017). "Reciprocally, the immunostimulatory capacity of IL-18 may promote the aggressiveness of myeloid leukemia cells." (PMID 20003308, 2009).
myositis (3 papers, 2020 to 2022). "Previous studies have shown that an increased serum IL18 correlated with ILD in DM, and that IL18 was expressed in muscle infiltrating cells of patients with myositis." (PMID 35517781, 2022).
neuropathic pain (3 papers, 2017 to 2023). Chronic pain caused by damage to nerve fibers. "We further found that CKO of neuronal FcγRI in the DRG or Syk inhibition can attenuate CCI‐induced Syk activation and NF‐κB p65 activation in DRG neurons and decrease NLRP3, IL‐1β, and IL‐18 expression levels in DRG after neuropathic pain." (PMID 36727833, 2023). "Several pro-inflammatory cytokines, including IL-1β, IL-6, IL-18, and TNF-α, have been implicated in the development of neuropathic pain." (PMID 35770074, 2022). "Moreover, Wnt, a downstream effecter of Kindlin-1, has been found to stimulate the release of pro-inflammatory cytokines, such as TNF-α and IL-18, in models of neuropathic pain." (PMID 28058534, 2017).
ovarian dysfunction (3 papers, 2021 to 2025). The inability of the ovaries to function. "Based on this report and the results of the present study, it can be assumed that IL‐18 might cause ovarian dysfunction and subsequent impaired fertility." (PMID 33459528, 2021). "While IL-6 plays a dual role (both pro- and anti-inflammatory), IL-18 is predominantly pro-inflammatory and directly exacerbates metabolic and ovarian dysfunction." (PMID 40385768, 2025).
paracoccidioidomycosis (3 papers, 2020 to 2025). A systemic fungal infection caused by Paracoccidioides brasiliensis that is most often seen in immunocompromised patients. "Polymorphisms related to IL12, IL18 and IFN were investigated in paracoccidioidomycosis patients separated in terms of their clinical presentations in acute form (AF), multifocal chronic (MC), or unifocal chronic (UC) forms of PCM and non-infected controls." (PMID 33668671, 2021).
pertussis (3 papers, 2014 to 2024). A contagious bacterial respiratory infection caused by Bordetella pertussis. "This may indicate that pertussis induces some IL-12 and IL-18 (such that LCC is redundant in these assays), whereas H1N1 may be a poor inducer of IL-12 and IL-18 but a better inducer of IL-2 or other accessory cytokines." (PMID 25855356, 2015).
plaque psoriasis (3 papers, 2014 to 2025). "Serum levels of the inflammatory mediators IL-6, IL-8, IL-12, IL-18, TNF-α and INF-γ were found to be elevated in plaque psoriasis." (PMID 24651659, 2014).
psychosis (3 papers, 2021 to 2024). "In a study of 96 adolescents (including 33 patients with psychotic disorders), fasting venous blood revealed that patients with early-onset psychosis had elevated levels of circulating IL18." (PMID 35599764, 2022). "Our results were similar to the previous clinical report that both levels of IL-18 and IL-18/IL-18BP ratios were significantly higher in patients with early-onset psychosis (EOP) aged 12–18 years than in age-matched healthy controls." (PMID 33441182, 2021).
pulmonary sarcoidosis (3 papers, 2009 to 2023). Sarcoidosis affecting the lung parenchyma. "What is more, pulmonary sarcoidosis disease progression and IL-18 levels were found to be positively correlated." (PMID 37334374, 2023). "A meta-analysis of 32 studies totalling almost four hundred pulmonary sarcoidosis patients examined the link between IL-18 levels and pulmonary sarcoidosis." (PMID 37334374, 2023). "Significantly elevated levels of IL-18 have been found in serum and BAL fluids (BALF) of patients with pulmonary sarcoidosis and have been shown to play a significant role in the immunopathogenesis of the sarcoid granuloma formation." (PMID 36314034, 2022).
SAPHO syndrome (3 papers, 2016 to 2024). SAPHO syndrome (acronym for Synovitis, Acne, Pustulosis, Hyperostosis and Osteitis) is an auto-inflammatory disease, mainly characterized by the association of neutrophilic cutaneous involvement and chronic osteomyelitis. "Interleukin-18 (IL-18) plays a critical role in the inflammatory and pathogenic mechanisms of SAPHO syndrome, affecting both innate and adaptive immune responses." (PMID 39286247, 2024). "By affecting both immune and bone cells, IL-18 plays a critical role in the pathogenesis of SAPHO syndrome, exacerbating the inflammatory and bone remodeling processes." (PMID 39286247, 2024). "Elevated levels of IL-18, observed in conditions with similar inflammatory profiles, suggest its involvement in sustained inflammatory processes in SAPHO syndrome." (PMID 39286247, 2024). "IL-18 is key in activating Th1 and NK cell responses, enhancing the production of IFN-γ by these cells, thereby exacerbating the inflammatory response in SAPHO syndrome." (PMID 39286247, 2024).
severe acute respiratory syndrome (3 papers, 2020 to 2023). A viral respiratory infection caused by the SARS coronavirus. "In models of lung infection, avian influenzae H5N1 and H7N9, which contain a PB1–F2 protein, persistently activate NLRP3, resulting in persistently elevated levels of IL-18, inducing IFN-gamma, and a subsequent cytokine storm in a manner reminiscent to severe acute respiratory syndrome (SARS)." (PMID 36823262, 2023).
sickle cell disease (3 papers, 2016 to 2020). Sickle cell anemias are chronic hemolytic diseases that may induce three types of acute accidents: severe anemia, severe bacterial infections, and ischemic vasoocclusive accidents (VOA) caused by sickle-shaped red blood cells obstructing small blood vessels and capillaries. "Genome-wide analyses have identified FUCA2 and IL-18 as novel genes associated with diastolic function in African Americans with sickle cell disease." (PMID 32475352, 2020).
skin sensitization (3 papers, 2020 to 2024). An immunological response to previous exposure to a substance which results in an inflammatory skin reaction. "After exposing the skin cells to the recycled materials for 48 h, the release of the proinflammatory cytokines IL-18 and TNF-α, which serve as indicators of potential skin sensitization, was measured in the cell culture medium using ELISA, following the manufacturer’s instructions." (PMID 37765629, 2023).
spinal cord injury (3 papers, 2023 to 2026). Penetrating and non-penetrating injuries to the spinal cord resulting from traumatic external forces (e.g., WOUNDS, GUNSHOT; WHIPLASH INJURIES; etc.). "In the case of spinal cord injuries, inflammasome activation mediates the inflammatory response through IL-18 and IL-1β with the activation of T helper lymphocytes (LTh1)." (PMID 36826052, 2023).
status epilepticus (3 papers, 2015 to 2022). Status epilepticus is defined as a continuous seizure lasting more than 30 min, or two or more seizures without full recovery of consciousness between any of them. "Overexpression of GPR120 significantly alleviated epileptic activity, reduced neuronal death after status epilepticus (SE), downregulated the expression of IL-1β, IL-6, IL-18, and pyrin domain-containing protein 3 (NLRP3) inflammasome, whereas knockdown GPR120 showed the opposite effect." (PMID 35624482, 2022).
tendinopathy (3 papers, 2012 to 2024). "In conclusion, we found that the NLRP3/ASC-inflammasome controls the production of IL-1β, meanwhile, another ASC-dependent inflammasome is required to produce IL-18 in tendinopathy induced by sterile tissue degradation of the extracellular collagen matrix." (PMID 39468985, 2024). "In fact, various inflammatory mediators like TNF-alpha, IL-6, IL-15, IL-18 have been shown to play a role especially in wound healing after injury and in early stages of tendinopathy." (PMID 22480275, 2012). "Therefore, our results confirm that in tendinopathies, differential IL-1β and IL-18 production could be controlled by different inflammasomes." (PMID 39468985, 2024). "In this study, we found that NLRP3 controls the production of IL-1β in a mouse model of tendinopathy by sterile extracellular matrix degradation, while an alternative ASC-dependent inflammasome controls IL-18 production." (PMID 39468985, 2024).
thyroid cancer (3 papers, 2022 to 2025). "TNFRSF10B, TNFRSF10C, TNFRSF12A, UNC5B, PMAIP1, and IL18 had increased expression in thyroid cancer tissues, while NUAK2 was decreased." (PMID 39104814, 2024). "Protein expression of three PRGs was then determined, where CASP6 and IL18 were increased in thyroid cancer tissues, while CASP9 was down-regulated, which was also consistent with the bioassay results." (PMID 36675746, 2022). "The remaining 38 inflammatory cytokines, including IL-18, did not correlate with the risk of thyroid cancer." (PMID 40892159, 2025).